PLEKHM1 (pleckstrin homology and RUN domain containing M1)
Description:
Acts as a multivalent adapter protein that regulates Rab7-dependent and HOPS complex-dependent fusion events in the endolysosomal system and couples autophagic and the endocytic trafficking pathways. Acts as a dual effector of RAB7A and ARL8B that simultaneously binds these GTPases, bringing about clustering and fusion of late endosomes and lysosomes. Required for late stages of endolysosomal maturation, facilitating both endocytosis-mediated degradation of growth factor receptors and autophagosome clearance. Interaction with Arl8b is a crucial factor in the terminal maturation of autophagosomes and to mediate autophagosome-lysosome fusion. Positively regulates lysosome peripheral distribution and ruffled border formation in osteoclasts (By similarity). May be involved in negative regulation of endocytic transport from early endosome to late endosome/lysosome implicating its association with Rab7. May have a role in sialyl-lex-mediated transduction of apoptotic signals. Involved in bone resorption (By similarity). (Microbial infection) In case of infection contributes to Salmonella typhimurium pathogenesis by supporting the integrity of the Salmonella-containing vacuole (SCV) probably in concert with the HOPS complex and Rab7.
Synonyms: AP162; KIAA0356; B2; OPTA3; OPTB6
Tractability: Small molecule: a structure with a bound ligand is known. Antibody: UniProt places it where antibodies can reach, with high confidence. PROTAC: ubiquitination databases record sites on it; its protein half-life has been measured.
Gene: Protein-coding gene on chromosome 17 (45,435,900 to 45,490,758, reverse strand). Ensembl gene ENSG00000225190.
Subcellular location: Autolysosome membrane; Endosome membrane; Late endosome membrane; Lysosome membrane
Subcellular location (Human Protein Atlas): Vesicles
Gene Ontology:
Molecular function: protein binding
Biological process: autophagosome-lysosome fusion; late endosome to lysosome transport; lysosome localization; positive regulation of bone resorption; positive regulation of ruffle assembly
Cellular component: autolysosome; autolysosome membrane; endosome membrane; late endosome membrane; lysosomal membrane; lysosome
Genetic constraint (gnomAD): Loss-of-function variants: 29 observed, 91.35 expected, observed/expected ratio (o/e) 0.32, 90% interval 0.23 to 0.43. The synonymous counts are far from expectation, so gnomAD's model fits this gene poorly and the ratio says little. Missense variants: 897 observed, 1,336.8 expected, observed/expected ratio (o/e) 0.67, 90% interval 0.63 to 0.71. Synonymous variants: 423 observed, 570.79 expected, observed/expected ratio (o/e) 0.74, 90% interval 0.68 to 0.8.
Gene-disease validity (ClinGen):
ClinGen rates the evidence that PLEKHM1 causes each of these diseases.
autosomal recessive osteopetrosis 6 (autosomal recessive): Moderate.
osteopetrosis, autosomal dominant 3 (autosomal dominant): Limited.
Homologues: Orthologues: chimpanzee PLEKHM1 (99% identical), macaque PLEKHM1 (97% identical), rabbit PLEKHM1 (87% identical), pig PLEKHM1 (84% identical), mouse Plekhm1 (84% identical), rat Plekhm1 (84% identical), dog PLEKHM1 (82% identical), guinea pig PLEKHM1 (82% identical), tropical clawed frog plekhm1 (44% identical), zebrafish plekhm1 (42% identical), Caenorhabditis elegans cup-14 (21% identical), Drosophila melanogaster Plekhm1 (19% identical). Paralogues in human: PLEKHM3 (19% identical), RUBCN (15% identical), RUBCNL (13% identical), DEF8 (10% identical).
Diseases named in the same sentence as PLEKHM1 in open-access papers:
PLEKHM1 is named in the same sentence as 32 diseases in open-access papers, as found by Europe PMC text mining. Sharing a sentence is not in itself a finding about the gene and the disease. The quoted sentences say what the papers report.
osteopetrosis (21 papers, 2011 to 2024). Osteopetrosis, also known as marble bone disease, is a descriptive term that refers to a group of rare, heritable disorders of the skeleton characterized by increased bone density on radiographs. "Of the four remaining genes, human disease is already associated with variants in PLEKHM1 (OMIM #611497 osteopetrosis) and EPOR (OMIM #133100 erythrocytosis), but the family presented here does not exhibit either of these phenotypes." (PMID 32167558, 2020). "Previously, we and others identified mutations of Plekhm1 that cause osteopetrosis in rats and humans and osteopenia in a human patient." (PMID 25992615, 2015). "More recently, mutations of the PLEKHM1 gene have been identified as the cause of the osteopetrotic ia/ia (incisors absent) rat as well as a subset of patients with intermediate osteopetrosis." (PMID 22073305, 2011). "Sequence analysis of rat and human genomes has uncovered mutations in the PLEKHM1 gene in ia/ia rats and in a family with an intermediate form of osteopetrosis." (PMID 22073305, 2011). "Case 1 displayed a PLEKHM1 mutation, which correlated with the patient's osteopetrosis diagnosis." (PMID 39639855, 2024). "Intermediate forms of osteopetrosis are caused bydefects in the PLEKHM1 and SNX10 genes." (PMID 37465191, 2023). "Arl8b and PLEKHM1 interaction might have implications in the human disease osteopetrosis, a genetic disorder caused by loss-of-function mutations in PLEKHM1 that disrupt osteoclast function in bone resorption, resulting in disorganized bone structure." (PMID 28325809, 2017). "Importantly, mutations in an effector of RAB7, PLEKHM1, cause a form of osteopetrosis in humans." (PMID 37359363, 2023). "Our human disease and gene network analysis suggested a link between CCR5 and PLEKHM1 genes in the context of osteopetrosis." (PMID 38012303, 2023). "Additionally, studies have identified the PLEKHM1 gene, which plays a vital role in regulating intermediate autosomal osteopetrosis (an intermediate type of human osteopetrosis) and the endosomal/autophagy pathway in the human genome." (PMID 38146458, 2023). "Furthermore, a gene-disease enrichment analysis identified that PLEKHM1, a responsible gene for osteopetrosis, which regulates lysosomal trafficking in osteoclasts, was regulated by CCR5." (PMID 38012303, 2023). "Our results suggested a potential shared regulatory mechanism of PLEKHM1 for osteopetrosis and KSD." (PMID 37980427, 2023). "Extremely rare forms of osteoclast-rich osteopetrosis are caused by defects in the carbonic anhydrase 2 (CA2), pleckstrin homology and RUN domain-containing M1 (PLEKHM1), leucine-rich repeat kinase 1 (LRRK1) and melanocyte-inducing transcription factor (MITF) genes." (PMID 33970241, 2021). "Mutations in OSTM1, SNX10, and PLEKHM1 are rare and are also associated with forms of osteopetrosis characterized by the presence of non-functional osteoclasts (osteoclast-rich osteopetrosis)." (PMID 33081155, 2020). "Loss-of-function mutations in PLEKHM1 result in an intermediate or severe form of osteopetrosis in humans, with no or underdeveloped ruffled membranes in patient-derived osteoclasts, or altered endocytosis and autophagy in cells expressing the mutant gene." (PMID 33081155, 2020). "The other is Plekhm1, a large, multi-domain protein that also causes osteopetrosis in humans and in the incisors absent (ia) rat when truncated, and which causes osteopenia with focal sclerosis when carrying a gain-of-function point mutation." (PMID 25992615, 2015). "Loss-of-function mutations in the PLEKHM1 (pleckstrin homology domain–containing family M member 1) gene cause mild osteopetrosis in the ia (incisors absent) rat, as well as an intermediate form of human osteopetrosis." (PMID 30837952, 2019).
osteopetrosis (continued). "Various forms of recessive osteopetrosis have been reported, some of which are associated with the most severe phenotypes (including those caused by mutations in the TCIRG1, CLC7, and OSTM1 genes), whereas mutations in other genes (CAII and PLEKHM1) give a milder osteopetrotic phenotype." (PMID 23160729, 2013).
Parkinson disease (4 papers, 2013 to 2025). A progressive degenerative disorder of the central nervous system characterized by loss of dopamine producing neurons in the substantia nigra and the presence of Lewy bodies in the substantia nigra and locus coeruleus. "These genes, in combination with PLEKHM1 and HLA-DQB1 are also associated with the GWAS Catalog trait, “Parkinson’s disease” (level 0)." (PMID 37336921, 2023). "Variation in this region has been associated with Parkinson's disease (MAPT, PLEKHM1, NSF, c17orf69) progressive supranuclear palsy (MAPT), celiac disease (WNT3), bone mineral density (CRHR1) (NHGRI GWAS catalog) and intracranial volume." (PMID 23544013, 2013). "The loci within these eQTL scores have been reported to regulate expression of genes involved in various brain-related processes and disorders, such as neurite outgrowth and Parkinson’s disease (DCAKD, SLC35A4, SEC14L4, SRA1, NMT1, CPNE1, PLEKHM1, UBE3C)." (PMID 32066731, 2020).
ovarian carcinoma (3 papers, 2013 to 2025). A malignant neoplasm originating from the surface ovarian epithelium. "The shared regions, including RP11-259G18.1 (17:46267037), PLEKHM1 (17:45435900), KANSL1-AS1 (17:46193576), and LINC00886 (3:156747346), suggest common biological pathways and mechanisms, further strengthening the relevance of our findings to ovarian cancer susceptibility." (PMID 40301634, 2025). "Moreover, among genes affected by this CNV, PLEKHM1 (which is not deleted in Koolen–de Vries syndrome) is also considered as an ovarian cancer predisposing gene." (PMID 33503040, 2021).
autosomal recessive osteopetrosis (2 papers, 2025). An autosomal recessive form of osteopetrosis caused by mutation(s) in at least 8 genes related to osteoclast function. "Notably, mutations in the human ortholog of Plekhm1 have been implicated in autosomal recessive osteopetrosis, which results from improper lysosomal acidification and resorption of the extracellular bone matrix, a mechanism reminiscent of SFC acidification of nurse cells." (PMID 39752622, 2025).
COVID-19 (2 papers, 2022 to 2023). A disease caused by infection with severe acute respiratory syndrome coronavirus 2. "Similar with findings from CPASSOC, we found shared genes between COVID-19 and cancers that are related to hematologic systems (ABO), immune function (MUC1, PLEKHM1), and cell proliferation (KANSL1-AS1)." (PMID 37636041, 2023). "Among these TWAS significant genes, ABO (enriched in artery aorta and shared by EOC with all three COVID-19 phenotypes), CRHR1-IT1 (enriched in artery aorta and prostate), and PLEKHM1 (enriched in brain cortex) were located at pleiotropic loci identified in cross-trait meta-analysis." (PMID 37636041, 2023).
progressive supranuclear palsy (2 papers, 2013 to 2025). A rare late-onset neurodegenerative disease characterized by supranuclear gaze palsy, postural instability, progressive rigidity, and mild dementia. "The expression of PLEKHM1 seems to be intricately regulated, as the expression of PLEKHM1 is increased in the MAPT H1 haplotype, which is associated with AD, PD, progressive supranuclear palsy (PSP), and corticobasal degeneration." (PMID 40940751, 2025).
Salmonella Infections (2 papers, 2015 to 2023). Infections with bacteria of the genus SALMONELLA. "Very recent studies have highlighted the role of the host protein Plekhm1 in Salmonella infection." (PMID 26268777, 2015). "To test functionally the impact of RUFY3 on EL function, we performed Salmonella infection, since ARL8b/PLEKHM2/HOPS- and Rab7/PLEKHM1-dependent EL mobilizations are particularly important for the maturation of Salmonella-containing vacuoles (SCV) and bacterial replication in macrophages." (PMID 37463962, 2023).
schizophrenia (2 papers, 2023 to 2025). A major psychotic disorder characterized by abnormalities in the perception or expression of reality. "Disease-risk genes that overlapped across PD, ALS and schizophrenia were KANSL1-AS1 (microglia and oligodendrocytes) and KANSL1, ARHGAP27, and PLEKHM1 (microglia)." (PMID 40202986, 2025).
Anxiety (1 paper, 2021). Intense feelings of nervousness, tension, or panic often arise in response to interpersonal stresses. "It is noteworthy that 10 genes (KANSL1-AS1, CRHR1, CRHR1-IT1, SPPL2C, RP11-707O23.5, RP11-259G18.1, MAPT-AS1, LRRC37A4P, PLEKHM1, and DND1P1) showed TWS in both datasets (i.e., PsychENCODE and GTEx), implying these genes are promising candidate genes for anxiety." (PMID 34650599, 2021).
atherosclerosis (1 paper, 2024). A disease characterized by the build-up of fatty material and calcium deposition in the arterial wall resulting in partial or complete occlusion of the arterial lumen. "Mechanistic studies showed that MYBL1 knockdown inhibited autophagosome and lysosomal fusion in HUVECs by inhibiting PLEKHM1, thereby exacerbating atherosclerosis." (PMID 38797732, 2024). "Given the diverse effect of PLEKHM1 on different diseases, it is still unclear what role PLEKHM1 plays in the development of atherosclerosis." (PMID 38797732, 2024). "MYBL1 knockdown in HUVECs was involved in atherosclerosis by inhibiting PLEKHM1-induced autophagy, which provided a novel target of therapy for atherosclerosis." (PMID 38797732, 2024). "Our study aims to clarify the mechanism of MYBL1 in endothelial cells involved in atherosclerosis by regulating PLEKHM1-induced autophagy, and to provide new understanding of atherosclerosis." (PMID 38797732, 2024).
autism (1 paper, 2024). Persistent deficits in social interaction and communication and interaction as well as a markedly restricted repertoire of activity and interest as well as repetitive patterns of behavior. "The defective pre-pulse inhibition phenotype observed in high-functioning autism patients is validated in PLEKHM1 knockout models." (PMID 39038939, 2024).
bone marrow failure (1 paper, 2017). "The phenotype of IARO, previously associated with mutations in the PLEKHM1, CLCN7, and CA2 genes, 21, 24, is defined as asymptomatic at birth, with patients exhibiting fractures by the end of their first decade of life, while bone marrow failure and hepato-splenomegaly are rare." (PMID 28592808, 2017).
lung carcinoma (1 paper, 2020). "Predicted expression of seven genes was significantly (p < 5.0 × 10−4) associated with lung cancer risk: SECISBP2L, HLA-L, DISP2, MAPT, KANSL1-AS1, LRRC37A4P, and PLEKHM1." (PMID 31911640, 2020).
myopia (1 paper, 2022). "Patients with mutations c.141+4A>G in the CLCN7 gene and c.2902-9C>T in the PLEKHM1 gene had multiple fractures as well as sensorineural hearing loss, myopia, arthropathies, and ligamentous apparatus lesions." (PMID 35052464, 2022).
osteosclerosis (1 paper, 2025). Abnormally high bone density. "Rab7 role in lysosomal transport is further modulated by its interaction with Plekhm1, whose mutations are linked to osteosclerosis; Plekhm1 deficiency disrupts lysosomal anchoring to microtubules, impairing bone resorption." (PMID 40995561, 2025). "Additionally, ‘Pleckstrin homology domain-containing family M member 1’ (Plekhm1) interacts with Rab7 to regulate vesicular trafficking in osteoclasts, and its mutations (e.g., in Y949–R954/L1011–I1018 regions) disrupt lysosomal transport and cause osteosclerosis via NDE1/NDEL1-related pathways." (PMID 40995561, 2025).
neurodegenerative disease (3 papers, 2021 to 2025). A disorder of the central nervous system characterized by gradual and progressive loss of neural tissue and neurologic function. "Emerging genetic evidence highlights the role of pleckstrin homology and RUN domain-containing M1 protein (PLEKHM1), a critical regulator of autophagosome–lysosome fusion, in the pathogenesis of multiple neurodegenerative diseases." (PMID 40940751, 2025). "Two transcripts from another promising target for neurodegenerative disease, PLEKHM1, were both down-regulated by the H2H2 haplotype." (PMID 33804213, 2021). "Since alterations in PLEKHM1 expression levels, in either direction, were linked to neurodegenerative diseases and the lack of PLEKHM1 impairs the autophagy–lysosomal pathway, we were interested in the impact of PLEKHM1 overexpression." (PMID 40940751, 2025).
cancer (2 papers, 2021 to 2023). A tumor composed of atypical neoplastic, often pleomorphic cells that invade other tissues. "All these findings support the implication of KANSL1 and PLEKHM1 in cancer which may explain the phenotype of our two patients." (PMID 33503040, 2021).
infection (2 papers, 2015 to 2024). The state of being infected such as from the introduction of a foreign agent such as serum, vaccine, antigenic substance or organism. "One can hypothesise that Plekhm1 is unnecessary for the virulence in the mouse model of infection or that Plekhm1 needs SKIP to play its role in the infectious process." (PMID 26268777, 2015). "Several genes including MAP1LC3B, SQSTM1 and PLEKHM1 demonstrated a pattern wherein expression level was significantly downregulated upon SARS-CoV-2 infection (vs. no infection) in DMSO-treated ALOs and significantly upregulated in response to RMC-113 treatment." (PMID 38659941, 2024).
PLEKHM1 also shares sentences with these, for which no sentence is quoted: cardiac hypertrophy (2 papers); aortic stenosis (1); autosomal dominant osteopetrosis type 2 (1); celiac disease (1); cognitive decline (1); corticobasal degeneration (1); erythrocytosis (1); genetic disorder (1); hearing loss (1); Osteopenia (1); prostate carcinoma (1); psychiatric disorder (1); sensorineural hearing loss (1); Splenomegaly (1).